NCBP2 (nuclear cap binding protein subunit 2)
Diseases named in the same sentence as NCBP2 in open-access papers (continued):
Sharing a sentence is not in itself a finding about the gene and the disease.
tumor (19 papers, 2015 to 2025). "In addition, the mechanism underlying NCBP2 and the tumor microenvironment need further experimental validation." (PMID 40124611, 2025). "Then, we conducted a cancer type-based genetic alteration analysis of NCBP2 in the TCGA pan-cancer tumor samples." (PMID 40124611, 2025). "The expression of NCBP2 was correlated with genomic alteration, prognosis, immune response related pathways, tumor microenvironment, immune cell infiltration, TMB, and MSI in various cancers." (PMID 40124611, 2025). "We found that NCBP2 expression was significantly upregulated in tumour cells compared to normal human tissue samples from the GTEx consortium, and other cells in the tumour microenvironment." (PMID 36635327, 2023). "Most importantly, we construct tissue microarrays from 26 tumor specimens and 20 normal specimens, and further confirm that EIF4A1 and NCBP2 are associated with tumor progression and Gleason score." (PMID 36810782, 2023). "The tumor growth was significantly slower in nude mice implanted with NCBP2-knockdown Panc 05.04 cells." (PMID 38001714, 2023). "Since our studies indicate that NCBP2 is a novel tumour-promoting gene and very little is known about the downstream effector genes regulated by NCBP2, we performed DEA between top (n = 68) vs. bottom quartile (n = 69) NCBP2 expressing TCGA-OSCC samples." (PMID 36635327, 2023). "Consistently, immunohistochemical results revealed that the expression of Ki-67 was remarkably decreased in NCBP2-knockdown tumor tissues compared with the control group." (PMID 38001714, 2023). "Differential expression analysis revealed the upregulation of several tumour-promoting genes in patients with high NCBP2 expression." (PMID 36635327, 2023). "The protein expression levels of NCBP2 in tumor tissues were markedly upregulated compared to those in normal tissues." (PMID 35784919, 2022). "Most tumor cells expressed NCBP2, EIF3D, and NUDT4 suggesting that m7G-related genes may play a significant role in tumor development." (PMID 41406096, 2025). "Interestingly, our single-cell RNAseq analysis revealed significant expression of TFRC in dendritic cells and macrophages, whereas NCBP2 expression was almost entirely restricted to tumour cells." (PMID 36635327, 2023). "IHC-based assessment of NCBP2 protein levels could be employed as a companion diagnostic for potential NCBP2-targeting therapies, helping tailor treatment to patients whose tumours are driven by NCBP2." (PMID 36635327, 2023). "Through pseudo-time analysis, we identified genes such as NCBP2, EIF3D, and NUDT4 boost the occurrence and development of malignant tumor epithelial cells, providing guidance for identifying potential therapeutic targets for CRC." (PMID 41406096, 2025). "Expression of NCBP2 and TFRC is significantly higher in tumour cells compared to most normal human tissues." (PMID 36635327, 2023). "Our results showed that NCBP2 and EIF4A1 proteins were significantly highly expressed in tumor tissue and that the protein expression ofNCBP2 andEIF4A1 increased significantly with an increasing Gleason score." (PMID 36810782, 2023). "In tumor tissues, EIF4E and NCBP2 were highly expressed, while WDR4 and NCBP1 were moderately expressed." (PMID 35784919, 2022). "Lastly, 10 paired CRC tumor and paracancerous tissue samples were obtained, and qRT-PCR analyses revealed that EIF4E3 and GEMIN5 were downregulated in CRC, whereas NCBP2 was upregulated." (PMID 36482181, 2022). "The expression of CNV-amplified m7G regulators was markedly higher in HCC specimens than in normal control specimens, such as AGO2, NCBP2, GEMIN5 and LARP1, while the expression of EIF4E3 was significantly lower in tumor specimens." (PMID 36389726, 2022). "The expression levels of IGF2BP2, RAI2, SLC25A27, NCBP2, and EIF4B were greatly enhanced, as is the case in tumor development." (PMID 25978455, 2015).
tumor (continued). "Notably, DCPS manifested pronounced expression in both neoplastic and non‐neoplastic tissues, while DCP2, NCBP2, WDR4, and NUDT3 demonstrated intermediate expression across tumor and normal samples." (PMID 40485623, 2025). "TFRC protein has been shown to regulate the progression of several squamous epithelial tumours, however, no functional analysis has been performed on the ability of NCBP2 to regulate tumour progression." (PMID 36635327, 2023). "Third, the oncogenic capacities of NCBP2 have not been verified in a xenograft tumor model of nude mice." (PMID 35784919, 2022). "However, since we detected TFRC expression in the bone marrow and immune cells in the tumour microenvironment, TFRC-targeting might be less desirable compared to ablating NCBP2." (PMID 36635327, 2023). "The protein expressions of METTL1, NSUN2, EIF4G3, LARP1, NCBP1, and NCBP2 were higher in tumor tissues than in normal tissues; however, the protein expressions of WDR4, EIF4E1B, and NCBP2L were negative in both tumor and normal tissues." (PMID 35785179, 2022).
cancer (15 papers, 2020 to 2025). A tumor composed of atypical neoplastic, often pleomorphic cells that invade other tissues. "Subsequently, we further examined the association between NCBP2 and several biological process of specific cancer types." (PMID 40124611, 2025). "To elucidate the biological processes associated with NCBP2 in cancers, we performed DEGs analysis between the top (71–100%) and bottom (0–30%) NCBP2 expression subgroups in each cancer type." (PMID 40124611, 2025). "Subsequently, based on the DEGs, GSEA was executed across 33 cancer types to investigate the NCBP2-associated cancer processes." (PMID 40124611, 2025). "Gene Set Enrichment Analysis (GSEA) demonstrated that elevated NCBP2 was linked to immune and proliferation related pathways across multiple cancer types." (PMID 40124611, 2025). "The present study utilized the cBioPortal database to investigate the genetic alterations of nuclear cap binding protein subunit 2 (NCBP2) in pan-cancer." (PMID 40124611, 2025). "Collectively, this study provides evidence for elucidating immunotherapeutic effect of NCBP2 in a variety of cancers, which is likely to provide useful information for further research." (PMID 40124611, 2025). "In general, NCBP2 was positively correlated with stemness-indexes in most cancers, except for ACC, CHOL, LAML, PCPG, and SARC." (PMID 40124611, 2025). "The identification of core proteins NXF1 and NCBP2 as driver genes in this pathway provides new avenues for exploring the functional implications of the ubiquitin-proteasome system in cancer." (PMID 40522954, 2025). "Overall, these data suggested that NCBP2 plays a prognostic role in several cancers, but the roles were complicated and multifaceted across cancers." (PMID 40124611, 2025). "As a consequence, we further analyzed the relationship between the expression of NCBP2 and copy numbers in the top five cancers." (PMID 40124611, 2025). "In this study, we identified that a range of cancers exhibit alterations in NCBP2, with its expression being up-regulated in the majority of these cancers." (PMID 40124611, 2025). "In this study, NCBP2 was specifically examined across cancer types, which highlights the potential of NCBP2 from prognostic to immunotherapeutic aspects." (PMID 40124611, 2025). "The general alteration frequency of NCBP2 was relatively high in the top five cancers, which had an alteration frequency of >20% with “Amplification” as the primary type, while the most frequent NCBP2 alteration was identified among LUSC patients (>40%)." (PMID 40124611, 2025). "NCBP2 exhibited distinct genetic alterations in pan-cancer with an increased expression in 24/32, while decreased expression in 3/32, types of cancers." (PMID 40124611, 2025). "In conclusion, we comprehensively analyzed the role of NCBP2 across cancers, showing its potential in predicting prognosis and immunotherapeutic response." (PMID 40124611, 2025). "The biological pathways driven by eIF4E and NCBP2 overexpression differed although they both had cancer phenotypes." (PMID 40766477, 2025). "Kaplan–Meier and univariate or multivariate Cox regression analysis indicated that NCBP2 serve as a prognostic factor in several cancers, particularly in PAAD and UCEC." (PMID 40124611, 2025). "The Cancer Genome Atlas (TCGA) and online web tools were employed to analyze the correlation between NCBP2 and prognosis, genome instability, immune infiltration, immune response, cancer stemness, and chemotherapeutic efficacy in pan-cancer." (PMID 40124611, 2025). "We further assessed the expression levels of NCBP2 across cancers using integrated data from TCGA and GTEx databases." (PMID 40124611, 2025). "Although there are several reports revealing the high expression of NCBP2 in different cancer types, its specific function and related molecular mechanisms in cancer development are still unclear." (PMID 38001714, 2023).
cancer (continued). "The volcano plot revealed that the cancer-promoting proteins (NCBP2, AMD, MER34, ENC1, and COA4) were down-regulated, while the secretory glycoprotein (A1BG) and ROS-reducing protein (ASB6) were up-regulated in the treatment group." (PMID 35818360, 2022). "Here, we showed that natural peptides from T. stans inhibited the growth, migration and invasion of A549 cells by suppressing the expression of cancer-promoting proteins (NCBP2, AMD, MER34, ENC1, and COA4)." (PMID 35818360, 2022). "The cancer-promoting proteins (NCBP2, AMD, MER34, ENC1, and COA4) were suppressed, while the secretory glycoprotein (A1BG) and ROS-reducing protein (ASB6) were overexpressed in the treatment group." (PMID 35818360, 2022). "As observed in the genetic analysis, most cancers expressed altered levels of NCBP2." (PMID 40124611, 2025). "Inspired by the results of NCBP2 and cancer immunity, we speculated that NCBP2 might play a role in cancer stemness." (PMID 40124611, 2025). "Our findings showed that NCBP2 was positively correlated with stemness indexes in many cancers, suggesting it could be a target to overcome therapeutic resistance." (PMID 40124611, 2025). "A positive relationship between poor OS and NCBP2 was observed in UCEC, PAAD, LIHC, KIRP, KICH and KIRC as shown in the forest plot and patients with high expression of NCBP2 shown worse OS compared to patients with low expression of NCBP2 in all of the 6 cancers." (PMID 40124611, 2025). "This information suggested that NCBP2 may be involved in the immune response related pathways of cancers." (PMID 40124611, 2025). "Further investigation should focus on the function of the NCBP2 protein in cancer cells." (PMID 40124611, 2025). "According to the results of GSEA in pan-cancer, NCBP2 was closely related to immune related pathways, such as IFN-alpha response, IFN-gamma response, IL-6/JAK/STAT3 signaling, IL-2/STAT5 signaling, allograft-rejection pathways, inflammatory response, and TNF alpha signaling-via NFKB." (PMID 40124611, 2025). "In summary, these results provide evidences that the abnormal expression of NCBP2 may be involved in the immune response and progress of cancers." (PMID 40124611, 2025). "NCBP2 was differentially expressed in 27 of 32 kinds of cancers." (PMID 40124611, 2025). "Considering the role of cap-binding proteins in cancers and its potential role in cancer immunity, the CBC genomic alteration pattern of pan-cancer was revealed and we choose the gene NCBP2, which had the highest alteration frequency, for further investigation." (PMID 40124611, 2025). "We designed the pan-cancer analysis to investigate the expression, prognostic value, functional enrichment, immunotherapy predictive ability, stemness and potential targeting drugs of NCBP2 in various cancers." (PMID 40124611, 2025). "Notably, this level of overexpression is in the mid-range of expression seen in eIF4E and NCBP2 overexpression cancers and is thus physiologically relevant." (PMID 40766477, 2025). "Notably, NCBP2 expression were negatively associated with stromal score, immune score and ESTIMATE score in almost all cancer types except for ACC, CHOL, DLBC, KICH, LIHC and PAAD." (PMID 40124611, 2025). "The expression level of NCBP2 in PDAC was significantly higher than that in para-carcinoma tissue." (PMID 38001714, 2023). "Of note, we ascertained the cancer-promoting abilities of NCBP2 in HCC for the first time." (PMID 35784919, 2022). "For instance, the CNV of NCBP2 positively related to mRNA expression in nearly 30 cancer types." (PMID 36092891, 2022). "Notably, the roles of NCBP2 were complicated and multifaceted across different cancers." (PMID 40124611, 2025). "In this study, we revealed the correlation of NCBP2 with prognosis, microenvironment and stemness, indicating that NCBP2 might be a potential therapeutic target for more effective and personalized therapy strategies in pan-cancer." (PMID 40124611, 2025).
cancer (continued). "Additionally, an examination at the single-cell level indicated that NCBP2 was positively correlated with cell cycle progression, DNA damage, DNA repair, invasion, and stemness in most cancer types, while negatively correlated with apoptosis, inflammation, and hypoxia in certain cancers." (PMID 40124611, 2025). "Likewise, we found that NCBP2 expression was correlated with various immune infiltrating cells in each cancer, and the landscape of this correlation was different, which may be due to the other immune infiltration rates of certain tumors." (PMID 40124611, 2025). "Therefore, we further explored the role of NCBP2 in pan-cancer immunity." (PMID 40124611, 2025). "Therefore, our findings further expand the understanding of NCBP2 in regulating cancer progression." (PMID 38001714, 2023). "NCBP2 was correlated with overall survival (OS), disease-specific survival (DSS), and progression-free survival (PFS) in various cancers." (PMID 40124611, 2025). "Correlation analysis showed a significant correlation between NCBP2 and TMB, as well as MSI in several cancers, such as THYM and COAD." (PMID 40124611, 2025). "To further test our conclusion, we compared the expression level of NCBP2, c-JUN, and p-ERK between PDAC and para-carcinoma tissue by IHC staining on tissue microarray." (PMID 38001714, 2023). "As expected, the expression levels of NCBP2, c-JUN, and p-ERK were significantly higher in PDAC tissues than those in para-carcinoma tissues." (PMID 38001714, 2023). "Interestingly, we found that NCBP2 expression was significantly negatively correlated with CD8+ T cells, dendritic cells and neutrophils in various cancers, including COAD, HNSC and LUSC, which exhibited negatively enriched immune-related pathways." (PMID 40124611, 2025). "In general, a positive correlation was observed between NCBP2 and various immune cells, such as MDSC, progenitors of lymphoid, CD4+ T cell, CAF, neutrophils and monocytes, however a negative correlation was identified with NKT cells in various cancers." (PMID 40124611, 2025). "Similarly, the core proteins of NXF1 and NCBP2 in the Ubiquitin Mediated Proteolysis pathway, and RPS27A as a core protein in RNA Translation pathway, were also drive genes of the two cancers." (PMID 40522954, 2025). "What’s more, the expression of some writer genes (METTL1 and WDR4) and reader genes (AGO2 and NCBP2) was significantly upregulated in most cancers, while the expression of some eraser genes (NUDT12 and NUDT16) and some reader genes (EIF4E3) were downregulated in most cancers." (PMID 36339001, 2022). "However, the roles of NCBP2, MKRN3, and MRPL47 in cancers are still unclear." (PMID 33505420, 2020). "Furthermore, a negative association between NCBP2 and stromal score, immune score, and ESTIMATE score was detected, and a positive correlation was observed between NCBP2 and diverse immune cells as well as stemness-indexes in the majority of cancer types." (PMID 40124611, 2025).
NCBP2 also shares sentences with these, for which no sentence is quoted: head and neck squamous cell carcinoma (2 papers); adrenocortical carcinoma (1); breast carcinoma (1); Co-infection (1); colon cancers (1); epilepsy (1); fungal infection (1); gastric adenocarcinoma (1); liver fibrosis (1); mesothelioma (1); microcephaly (1); pancreatic adenocarcinoma (1); paraganglioma (1); pheochromocytoma (1); prostate carcinoma (1); sarcoma (1); urinary system tumors (1); uveal melanoma (1).